SHMT2 (serine hydroxymethyltransferase 2)
Diseases named in the same sentence as SHMT2 in open-access papers (continued):
Sharing a sentence is not in itself a finding about the gene and the disease.
lung carcinoma (continued). "Similarly, SHMT2 was significantly associated with CD8+ T cell infiltrates and highly expressed in breast, liver and lung cancer, and kidney renal papillary cell carcinoma." (PMID 37147729, 2023). "SHMT2 maintains lung cancer development mainly through classical regulation of 1C metabolism." (PMID 36699468, 2022). "SHMT1 and SHMT2 expression levels are cross-related in lung cancer cells; however, the mechanisms by which their expression is controlled to ensure the appropriate amounts of each isoform are unknown." (PMID 30809670, 2019). "SHMT1 and SHMT2 are up-regulated in patient-derived lung cancer tissue samples." (PMID 30809670, 2019). "Therefore, we hypothesized that the effect of miR-383-5p on lung cancer cell proliferation is related to the upregulation of SHMT2 and β-catenin." (PMID 38577602, 2024). "In lung cancer, SHMT1 indirectly influences mitochondrial SHMT2 expression and helps maintain a balance in the 1-carbon unit flux between the cytoplasm and mitochondria." (PMID 40738465, 2025). "Our analysis of Kaplan–Meier plots derived from data on 1925 lung cancer patients clearly confirmed the strong oncogenic role of HK2, LDHA, PHGDH, PSAT1, SHMT2, MTHFD2, c-Myc, and ATF4 (CREB-2) in lung cancer." (PMID 37233697, 2023). "Together with lung cancer cell lines A549 and H1299, which over-express both SHMT1 and SHMT2, we also used COLO320 cells that over-express SHMT2 but not SHMT1." (PMID 26717037, 2016). "We have previously shown that the expression of SHMT1 and SHMT2 are interconnected and there are differences in the response to SHMT modulation in A549 and H1299 lung cancer cell lines." (PMID 26717037, 2016). "In lung cancer, the targets of miR-615-5p includes IGF2, SHMT2 and AKT2." (PMID 37127605, 2023). "Next we tested if the lung cancer patient-derived-xenograft-derived cell line LPC43, which expresses a much higher level of endogenous SHMT2 compared with HeLa was sensitive to glycine deprivation as a function of SHMT2 expression." (PMID 32903271, 2020). "In this study we show that in addition to SHMT2, SHMT1 is overexpressed in samples from lung cancer patients and lung cancer cell lines, suggesting that, at least in this type of tumor, SHMT1 might have a relevant role." (PMID 25412303, 2014). "Furthermore, molecular docking and molecular dynamics simulations were performed for the selected lead compound, 2c, to investigate its binding interactions with serine hydroxymethyltransferase 2 (SHMT2), a mitochondrial protein differentially expressed in lung cancer." (PMID 40508093, 2025).
hepatocellular carcinoma (20 papers, 2016 to 2025). A malignant tumor that arises from hepatocytes. "Overexpression of serine hydroxymethyltransferase SHMT2 is also associated with poor prognosis in cancer patients, while downregulating this enzyme suppresses tumorigenesis in human hepatocellular carcinoma." (PMID 33243834, 2021). "miR-615-5p inhibits cell proliferation and migration by exerting a negative regulatory effect on SHMT2 in hepatocellular carcinoma." (PMID 40427537, 2025). "In hepatocellular carcinoma cells, an elevated L-serine pool was significantly correlated with SHMT2-mediated L-serine catabolism and elevated glycolytic flux." (PMID 39519335, 2024). "Inhibition of SHMT2 activity leads to the reduced proliferation of squamous cell carcinoma cells and prevents the growth of tumors derived from hepatoma cells in a xenograft model." (PMID 37749499, 2023). "C-MYC directly controls the transcription of PHGDH, PSAT1, PSPH, SHMT1, and SHMT2 in human hepatoma and HeLa cells." (PMID 37949226, 2023). "It was shown that mShmt (SHMT2 protein) in liver cancer cells converts Gly to Ser and its knockdown led to a significant reduction of intracellular Ser in Huh-7 hepatoma cells." (PMID 33023086, 2020). "SHMT2 knockout in hepatocellular carcinoma cell lines reduces cell growth and tumorigenicity in vitro and in vivo." (PMID 31828098, 2019). "Previous studies reported that SHMT2 can promote liver regeneration through the glycine-activated Akt/mTOR pathway, while a downregulated SHMT2 can suppress tumorigenesis in human hepatocellular carcinoma." (PMID 34149818, 2021). "Similarly, high SHMT2 expression in hepatocellular carcinoma (HCC) significantly correlates with decreased OS, lymph node metastases and HCC grade." (PMID 30857125, 2019). "On the same line, increased expression of serine hydroxymethyltransferase 2 (SHMT2), enzyme catalyzing the conversion of serine to glycine, was detected in HCC patients and was shown to promote proliferation in HepG2 hepatoma cell lines." (PMID 34680398, 2021). "SHMT2 expression was correlated with pathological grade, cell proliferation, migration, and EMT in hepatocellular carcinoma." (PMID 33163414, 2020). "In contrast, serum levels of serine are increased in humans with HCC compared with healthy subjects and high SHMT2 expression is associated with negative prognosis in human hepatocellular carcinoma." (PMID 31623280, 2019). "In hepatocellular carcinoma, miR-615-5p was able to target IGF2 and SHMT2 and inhibited cell proliferation, invasion, and metastasis." (PMID 30287504, 2018). "However, the therapeutic potential in targeting SHMT2 in hepatocellular carcinoma (HCC) is unknown." (PMID 27391339, 2016).
prostate carcinoma (17 papers, 2013 to 2025). A carcinoma that arises from epithelial cells of the prostate gland. "Elevated SHMT2 expression has been observed in prostate tumors with high Gleason scores, suggesting an association with more aggressive stages of prostate cancer." (PMID 40738465, 2025). "Also, expression of NME1 and SHMT2 is linked to poor prognosis in cancer patients, and in prostate cancer cells succinate enhances their expression." (PMID 33917317, 2021). "Importantly, high expression of NME1 was associated to a worse disease-free survival in prostate cancer patients in the TCGA dataset, and high SHMT2 expression in the TCGA and the Glinsky datasets." (PMID 33917317, 2021). "In LASCPC-01 cells, higher expression levels of genes encoding SHMT1 and SHMT2 and decreased availability of serine and glycine has been observed, indicating a higher demand of serine and glycine for multiple purposes in this aggressive subtype of prostate cancer." (PMID 31035489, 2019). "On the contrary, SHMT2 functions as a tumor suppressor and negatively regulates proliferation and metastasis in prostate cancer." (PMID 40097394, 2025). "Conversely, another study reported high SHMT2 expression in early-stage prostate cancer, with significant downregulation in aggressive late-stage tumors." (PMID 40738465, 2025). "Elevated expression of SHMT2 has been documented in various human cancers, including colorectal, lung, breast, ovarian, and prostate cancers, with higher expression levels correlating with poor prognosis in tumor tissues." (PMID 41013856, 2025). "In prostate cancer cells, the expression of SHMT2 is upregulated under the regulation of the typical JAK2/STAT3 pathway, affecting the early inflammatory response of cancer." (PMID 38594513, 2024). "This is supported by the recent evidence prostate cancer cell proliferation is dependent on the downregulation of SHMT2." (PMID 36959541, 2023). "Knockdown of SHMT2 attenuated the growth of prostate cancer cells (LNCaP, C4-2B, DU145, and PC3 cells) as well as various cancer cell lines including glioblastoma line LN229 and colon cancer cell lines HCT116 and SW480 following gene silencing by siRNA." (PMID 33637676, 2021). "This discovery matched the previous finding that the role of the STAT3/SHMT2/PKM2 loop was found to convert prostate cancer to a more aggressive phenotype." (PMID 33163414, 2020). "The evaluation of prostate cancer tumor tissues with Gleason scores of 6 and 9 confirmed the trend in the expression levels of SHMT2 and PKM2, and the alternative phosphorylation of STAT3 already found in the two cell lines utilized in this study." (PMID 31500219, 2019). "However, in prostate cancer, SHMT2 displays a more complex expression pattern, being elevated in early-stage or low-grade tumors but reduced in more advanced cases, suggesting a stage-dependent role." (PMID 40738465, 2025). "SHMT2 is highly expressed in early-stage prostate cancer compared with benign prostate tissue." (PMID 40738465, 2025). "Collectively, these studies suggest that SHMT2 may exert stage-specific effects on prostate cancer progression and metastasis, while the role of SHMT1 in this process remains largely unexplored." (PMID 40738465, 2025). "Additionally, high SHMT2 expression in prostate cancer has been linkedto a shift in cell metabolism toward anaerobic metabolism by decreasing serine levels and activating STAT3 transcription." (PMID 37108312, 2023). "This condition could constitute the breeding ground for the evolution of prostate cancer towards a more aggressive form (G9), involving a change in SHMT2 and PKM2 status through the IL-6/JAK2/STAT3 pathway." (PMID 31500219, 2019). "Given its key part in energy metabolism and its link to the protein STAT3, SHMT2 could represent a missing piece to further understand the molecular mechanisms responsible for the transition of prostate cancer towards a more aggressive phenotype." (PMID 31500219, 2019).
prostate carcinoma (continued). "Furthermore, upregulated SHMT2 expression increased the aggressiveness of prostate cancer cells." (PMID 34476002, 2021). "Chronic inflammation might thus prime the transition of PCa cells towards more advanced stages, and SHMT2 could represent a missing factor to further understand the molecular mechanisms responsible for the transition of prostate cancer towards a more aggressive phenotype." (PMID 31500219, 2019). "Recently, a potential role of SHMT2 has been proposed as a modulator of STAT3, a master regulator of energy metabolism, which is involved in the transition of prostate cancer towards a more aggressive phenotype." (PMID 33917317, 2021). "Further examination in publicly available prostate cancer transcriptome datasets confirmed NME1 and SHMT2 as consistently upregulated in prostate tumor cohorts." (PMID 33917317, 2021). "It has been suggested that SHMT2 is downstream of signal transducer and activator of transcription 3 (STAT3) and plays a key role in the conversion of prostate cancer to a more aggressive phenotype." (PMID 33163414, 2020). "We evaluated the expression levels of SHMT2, PKM2, and HIF-1α in prostate cancer tissues with different Gleason scores collected from human patients." (PMID 31500219, 2019). "SHMT2 and STAT3 jointly regulate prostate cancer metabolism and promote tumor progression." (PMID 40738465, 2025). "Targeting SHMT2 or H4K12 lactylation may suppress glycolysis and enhance chemotherapy/immunotherapy efficacy in prostate cancer." (PMID 41458606, 2025). "Furthermore, previous study revealed a potential novel role for SHMT2 as a downstream element of the STAT3 signaling pathway, and this molecular mechanism may be responsible for the transition of prostate cancer towards a more aggressive phenotype." (PMID 36077112, 2022).
colon cancer (16 papers, 2017 to 2024). "We screened 66 differentially expressed genes associated with CRC progression in 224 colon cancer tissues and 165 adjacent normal tissues from three GEO data sets and found that SHMT2 is important in CRC metabolism." (PMID 33990700, 2021). "In colon cancer, acetylation of Lys95 in SHMT2 disrupted its tetramer structure and inhibited its enzymatic activity; this acetylation also promoted SHMT2 degradation through the ubiquitin‐lysosome pathway." (PMID 38460155, 2024). "Studies have shown that the expression of SHMT2 is upregulated in many types of cancer, including breast cancer, liver cancer, gastric cancer, and colon cancer." (PMID 38460155, 2024). "Sirt3 KO mice contained a significantly decreased number of colon tumors, and the expression level of SHMT2 was dramatically lower in Sirt3 KO cancer cells." (PMID 30367038, 2018). "Our findings demonstrate that acetyl-mimetic substitution at lysine-95 impaired the ability of SHMT2 to support SW480 colon cancer cell proliferation and tumor growth." (PMID 30367038, 2018). "Taken together, these data indicate that acetylated SHMT2 cannot effectively utilize serine, which inhibits the rapid proliferation of colon cancer cells." (PMID 30367038, 2018). "Our study found that SHMT2 regulates the proliferation of colon cancer through G1/S phase arrest." (PMID 35211429, 2022). "Similarly, LINC01234 acted as a ceRNA of miR-642a-5p, resulting in the suppression of the endogenous serine hydroxymethyl transferase 2 (SHMT2), suggesting that the LINC01234-miR642a-5p-SHMT2 axis plays a key role in colon cancer." (PMID 31941509, 2020). "Furthermore, LINC01234 enhances colon cancer cell proliferation via the upregulation of serine hydroxymethyltransferase 2 (SHMT2) by competitively binding with miR-642a-59." (PMID 33246471, 2020). "In situ proteomic profiling of curcumin targets in a HCT116 colon cancer cell line reported 197 curcumin-binding proteins, including PKM1, PKM2 and SHMT2." (PMID 32121279, 2020). "Although MTHFD2 and SHMT2 were highly expressed in colon cancer cells, DHFR had a very low or undetectable expression in colon cancer cells." (PMID 29321536, 2018). "Recent studies demonstrated that SHMT2 is necessary for sustaining mitochondrial translation in the Jurket human leukemic and HCT116 human colon cancer cells." (PMID 30456347, 2018). "TYMS, SHMT2, GALT, RENBP, and AMDHD2 were among the metabolic genes that had an unfavorable expression in colon cancer, meaning that their high expression in patients treated with 5-FU was associated with poorer prognosis." (PMID 29026541, 2017).
bladder cancer (14 papers, 2016 to 2025). "Additionally, studies on bladder cancer have shown that SHMT2 overexpression promotes tumor cell growth and is associated with a poor prognosis." (PMID 38577602, 2024). "Through metabolomics and transcriptomic analysis we identified that loss of AGL makes bladder cancer cells dependent on Serine Hydroxymethyltransferase 2 (SHMT2) driven glycine synthesis and Hyaluronic Acid (HA) Synthase 2 (HAS2) driven HA synthesis for aggressive growth." (PMID 29682180, 2018). "In summary, our study demonstrated how SHMT2 functions in bladder cancer cells and suggested its potential molecular targets, which can be served as valuable therapeutic targets for bladder cancer in future." (PMID 41347062, 2025). "As SHMT2 expression is up-regulated, E-cadherin expression increases and N-cadherin expression decreases, thereby impairing the invasion ability of bladder cancer cells." (PMID 38594513, 2024). "SHMT2, as one of the serine hydroxymethyltransferase isozymes, is a potential cancer driver due to its influence on bladder cancer development, migration, and apoptosis." (PMID 38594513, 2024). "Our findings revealed that a decrease in SHMT2 expression level leads to the decrease in the proportion of cells in the G0/G1 stage of bladder cancer cells." (PMID 38594513, 2024). "The decrease in SHMT2 expression level has been found to weaken the in vitro migration ability and decrease the proliferation ability of bladder malignant tumor cells." (PMID 38594513, 2024). "Higher SHMT2 expression correlates with a worse prognosis or an aggressive phenotype in oral squamous cell carcinoma, bladder cancer, gastrointestinal tumors and other cancers." (PMID 37749499, 2023). "Overexpression of SHMT2 was correlated with a poor prognosis and promoted tumor growth in bladder cancer and thyroid cancer." (PMID 36213384, 2022). "Studies have shown that high expression of SHMT2 may promote tumor proliferation in bladder cancer, rhabdomyosarcoma, esophageal cancer and diffuse large B-cell lymphoma." (PMID 40097394, 2025). "Meanwhile, SHMT2 affects the growth, migration and apoptosis of bladder cancer cells in vitro." (PMID 41347062, 2025). "In conclusion, the SHMT2 gene plays a role in the malignant biological progress of bladder cancer." (PMID 38594513, 2024). "Similarly, the mitochondrial SHMT2 knockdown in bladder cancer cells leads to ROS accumulation and apoptosis." (PMID 38830901, 2024). "Considering the existing data, previous bioinformatics analysis, and transcriptome sequencing results, it can be inferred that SHMT2, one of the two isozyme genes of serine hydroxymethyltransferase, is more likely to be a potential driver of bladder cancer than SHMT1." (PMID 38594513, 2024). "However, the expression of SHMT2 in clinical tissues of bladder cancer was found to be higher than that in corresponding paracancerous tissues (*P < 0.05)." (PMID 38594513, 2024). "In addition, many researchers have also proposed that SHMT2 overexpression predicts a poor prognosis and promotes progression in various cancers, including bladder cancer, oral cancer, kidney cancer, and lymphoma." (PMID 36077112, 2022). "SHMT2 was overexpressed in many tumors, however, the role of SHMT2 in bladder cancer (BLCA) remains unclear." (PMID 34149818, 2021). "Notably, E-cadherin and N-cadherin may play a role in the SHMT2 regulatory network and influence the invasion ability of bladder cancer cells as SHMT2 expression changes." (PMID 38594513, 2024). "Additionally, SHMT2 affects the growth, migration, and apoptosis of bladder cancer cells in vitro." (PMID 38594513, 2024). "Regrettably, the research potential of this gene has not been fully realized in our current research progress, especially regarding the mechanism of interaction between SHMT2 and ECM receptors in the progression of bladder cancer." (PMID 38594513, 2024).
bladder cancer (continued). "After transient knockdown of the SHMT2 gene expression, Western Blot was performed to detect changes in invasion-related genes E-cadherin, N-cadherin, and MMP2 in bladder cancer cells T24 and J82." (PMID 38594513, 2024). "At the same time, the research of SHMT2 in bladder cancer is not very in-depth, and its downstream targets have not been well revealed." (PMID 41347062, 2025). "In the subsequent analysis of the SHMT2 gene using the same method, it was found that the expression of SHMT2 in bladder cancer was significantly higher than that in normal tissue, and the results of the three groups exhibited the same trend (P < 0.001)." (PMID 38594513, 2024). "Lowering AGL enhanced tumour growth by increasing glycine synthesis through increased expression of serine hydroxymethyltransferase 2 (SHMT2), whilst depletion of the SHMT2 rescues the effects of tumour growth of bladder cancer cells without AGL." (PMID 26882899, 2016).